TNK2 (tyrosine kinase non receptor 2)
Description:
Non-receptor tyrosine-protein and serine/threonine-protein kinase that is implicated in cell spreading and migration, cell survival, cell growth and proliferation. Transduces extracellular signals to cytosolic and nuclear effectors. Phosphorylates AKT1, AR, MCF2, WASL and WWOX. Implicated in trafficking and clathrin-mediated endocytosis through binding to epidermal growth factor receptor (EGFR) and clathrin. Binds to both poly- and mono-ubiquitin and regulates ligand-induced degradation of EGFR, thereby contributing to the accumulation of EGFR at the limiting membrane of early endosomes. Downstream effector of CDC42 which mediates CDC42-dependent cell migration via phosphorylation of BCAR1. May be involved both in adult synaptic function and plasticity and in brain development. Activates AKT1 by phosphorylating it on 'Tyr-176'. Phosphorylates AR on 'Tyr-267' and 'Tyr-363' thereby promoting its recruitment to androgen-responsive enhancers (AREs). Phosphorylates WWOX on 'Tyr-287'. Phosphorylates MCF2, thereby enhancing its activity as a guanine nucleotide exchange factor (GEF) toward Rho family proteins. Contributes to the control of AXL receptor levels. Confers metastatic properties on cancer cells and promotes tumor growth by negatively regulating tumor suppressor such as WWOX and positively regulating pro-survival factors such as AKT1 and AR. Phosphorylates WASP.
Synonyms: ACK-1; ACK1; p21cdc42Hs; ACK
Tractability: Small molecule: a structure with a bound ligand is known; a high-quality ligand is known; it has a high-quality binding pocket; it belongs to a druggable protein family. Antibody: UniProt places it where antibodies can reach, with high confidence; its Gene Ontology location is reachable by antibodies, with high confidence; the Human Protein Atlas places it where antibodies can reach. PROTAC: it is named in the literature on targeted protein degradation; UniProt records ubiquitination sites on it; ubiquitination databases record sites on it; its protein half-life has been measured; a small molecule that binds it is known.
Target class: Tyrosine protein kinase Ack family; TK protein kinase group; Enzyme; Protein Kinase; Kinase
Chemical probes: PD134244, PD134245, SYN-DFCI-00114 (high quality), XMD8-87 (high quality)
Gene: Protein-coding gene on chromosome 3 (195,863,364 to 195,911,945, reverse strand). Ensembl gene ENSG00000061938.
Subcellular location: Cell membrane; Nucleus; Endosome; Cell junction, adherens junction; Cytoplasmic vesicle membrane; Cytoplasmic vesicle, clathrin-coated vesicle; Membrane, clathrin-coated pit; Cytoplasm, perinuclear region; Cytoplasm, cytosol
Subcellular location (Human Protein Atlas): Plasma membrane; Vesicles
Pathways (Reactome):
Signal Transduction: Signaling by LTK
Gene Ontology:
Molecular function: epidermal growth factor receptor binding; identical protein binding; protein binding; protein serine kinase activity; protein serine/threonine/tyrosine kinase activity; protein tyrosine kinase activity; ubiquitin protein ligase binding; GTPase inhibitor activity; non-membrane spanning protein tyrosine kinase activity; WW domain binding; ATP binding; protein kinase activity; protein serine/threonine kinase activity
Biological process: phosphorylation; positive regulation of peptidyl-tyrosine phosphorylation; regulation of clathrin-dependent endocytosis; cell surface receptor signaling pathway; small GTPase-mediated signal transduction; signal transduction
Cellular component: clathrin-coated pit; clathrin-coated vesicle; cytoophidium; cytoplasm; Grb2-EGFR complex; membrane; nucleus; plasma membrane; cytosol; endosome; adherens junction; cytoplasmic vesicle membrane; perinuclear region of cytoplasm
Genetic constraint (gnomAD): Loss-of-function variants: 83 observed, 97.54 expected, observed/expected ratio (o/e) 0.85, 90% interval 0.71 to 1.02. The synonymous counts are far from expectation, so gnomAD's model fits this gene poorly and the ratio says little. Missense variants: 1,665 observed, 1,419 expected, observed/expected ratio (o/e) 1.17, 90% interval 1.13 to 1.22. Synonymous variants: 804 observed, 605.39 expected, observed/expected ratio (o/e) 1.33, 90% interval 1.25 to 1.41.
Homologues: Orthologues: macaque TNK2 (98% identical), chimpanzee TNK2 (97% identical), pig TNK2 (95% identical), rat Tnk2 (94% identical), mouse Tnk2 (93% identical), dog TNK2 (93% identical), guinea pig TNK2 (92% identical), rabbit TNK2 (72% identical), zebrafish tnk2a (57% identical), Drosophila melanogaster Ack (35% identical). Paralogues in human: TNK1 (26% identical), ABL2 (19% identical), ABL1 (19% identical), PTK2 (17% identical), PTK2B (15% identical), FRK (13% identical), FYN (13% identical), JAK2 (13% identical), LCK (13% identical), TYK2 (13% identical), FGR (13% identical), YES1 (13% identical), and 20 more.
Diseases named in the same sentence as TNK2 in open-access papers:
TNK2 is named in the same sentence as 81 diseases in open-access papers, as found by Europe PMC text mining. Sharing a sentence is not in itself a finding about the gene and the disease. The quoted sentences say what the papers report.
prostate carcinoma (33 papers, 2010 to 2024). A carcinoma that arises from epithelial cells of the prostate gland. "The TNK2 gene has been found to be amplified in primary lung, ovarian and prostate cancers and TNK2 overexpression is also associated with poor clinical outcomes." (PMID 26356563, 2015). "The levels of activated ACK within prostate cancer biopsies positively correlate with progression to the final castration-resistant prostate cancer (CRPC) stage and the presence of TNK2 alterations are associated with reduced survival." (PMID 37194323, 2023). "In prostate cancer, TNK2 participates in a feed-forward epigenetic circuit involving ACK1/pY88-H4/WDR5/MLL2/AR and is necessary for malignant cancer." (PMID 34421982, 2021). "Genes previously implicated in prostate cancer (PAK4, TNK2) and genital dysplasia (ROR2) also demonstrated mutations." (PMID 28423512, 2017). "ACK1/TNK2 tyrosine phosphorylates AR at Y267 in androgen deprived conditions of prostate cancer cells." (PMID 26546517, 2015). "TNK2, also known as ACK1 (activated Cdc42-associated kinase), is a non-receptor tyrosine kinase which has been shown to be frequently amplified or mutated in multiple human cancers including breast, esophageal, lung, ovarian, pancreatic and prostate cancer." (PMID 27902967, 2017). "Targeting key autophagic signaling pathways, such as TNK2/ACK1-mediated phosphorylation of ATP5F1A, can hinder prostate cancer progression by promoting mitophagy and reducing tumor growth." (PMID 39409882, 2024).
breast carcinoma (30 papers, 2008 to 2025). "Although TNK2 has also been reported to be amplified and mutated in multiple cancers, in breast cancer, its activation is likely to be facilitated by receptor tyrosine kinases that correlate with disease progression as well as survival." (PMID 27902967, 2017). "Subsequently, we studied the role of TNK2 on mammosphere formation, which is commonly used to indicate cellular stemness, an important tumorigenic hallmark in breast cancer." (PMID 27902967, 2017). "A recent immunohistochemistry-based study showed that high phosphorylation levels of TNK2 are associated with poor prognosis of breast cancer patients." (PMID 26356563, 2015). "We subsequently observed that TNK2 associates with activated EGFR in breast cancer cells in a TNK2-kinase-independent manner, and furthermore that it functions to maintain EGFRs on the cell surface." (PMID 18435854, 2008). "Consistent with the idea of an alternative mechanism for TNK2, we observed that TNK2 associates with activated EGFR in breast cancer cells in a TNK2-kinase-independent manner." (PMID 18435854, 2008). "However, when a subpopulation of 237 high grade basal-like breast cancer tumors were selected for the analysis, high TNK2 expression levels were significantly associated with poorer patient outcomes (p<0.01)." (PMID 27902967, 2017). "TNK2 (also known as ACK1) associates with EGFR in cancer cells to maintain EGFR on the cell surface and enhance human breast cancer cell migration and invasion." (PMID 33213062, 2020). "Further, expression of activated TNK2 was positively correlated with the severity of disease progression, and inversely correlated with the survival of breast cancer patients." (PMID 27902967, 2017). "To address the role of TNK2 in aggressive breast cancers, we established a lentiviral-based Tet-ON inducible shRNA knockdown system to suppress TNK2 expression in a regulated fashion." (PMID 27902967, 2017). "In the current study, we show that high expression of TNK2 in breast cancer cell lines correlates with high proliferation, invasion and colony forming ability." (PMID 27902967, 2017). "Further, analysis of breast cancer patient survival data revealed that high TNK2 expression is significantly correlated with worse outcome of high-grade TNBC patients." (PMID 27902967, 2017). "Initially, we observed that targeting of TNK2 by siRNA in human breast cancer cells resulted in distinct cytoskeletal and morphological changes, potentially indicative of changes in the motile properties of these cells." (PMID 18435854, 2008). "Significantly we found that silencing of BCAR1, a proposed downstream mediator of TNK2, inhibits breast cancer cell invasion via a mechanism distinct from the EGFR." (PMID 18435854, 2008). "We observed that targeting of TNK2 by siRNA in breast cancer cells resulted in distinct morphological changes characterised by a stellate appearance and an absence of protrusions at membrane edges." (PMID 18435854, 2008). "It has been suggested previously that phosphorylation of TNK2 might correlate with breast cancer progression; however, the functional significance of TNK2 expression and its role in breast cancer biology — particularly in TNBCs — has not been well elucidated." (PMID 27902967, 2017). "Finally, we find that high levels of TNK2 expression in high-grade basal-like breast cancers correlates significantly with poorer patient outcome." (PMID 27902967, 2017). "Our data now indicate that the same is true for TNK2, since the significant reduction of cell surface EGFRs we observed by TNK2 silencing was accompanied by a parallel decrease in the migratory capacity of the breast cancer cells." (PMID 18435854, 2008). "TNK2 mRNA expression level is lowest in normal breast and highest in TNBC comparing to other ER+ luminal and HER+ breast cancers." (PMID 27902967, 2017).
breast carcinoma (continued). "Of note, in ER positive breast cancer cells, estrogen can activate ER and induce SIAH2 expression that subsequently ubiquitinates TNK2 and reduces TNK2 expression." (PMID 27902967, 2017). "Because of the effect of TNK2 siRNA on the cell surface EGFR population, we wanted to determine the effect of EGFR activation on breast cancer cell behaviour." (PMID 18435854, 2008). "In accordance, TNK2 silencing by siRNA led to a significant reduction in cell surface EGFR and to a concomitant decrease in the migratory and invasive capacity of breast cancer cells." (PMID 18435854, 2008). "Immunohistochemical studies of tissue microarray revealed increased activation of non-receptor tyrosine kinase, ACK1 (also known as TNK2) in most of the breast cancer subtypes, independent of their hormone receptor status." (PMID 37330596, 2023). "We examined a range of breast cancer cell lines with varying levels of EGFR and TNK2." (PMID 18435854, 2008). "This confirms our hypothesis that TNK2 can operate separately from BCAR1 to facilitate migration and invasion of breast cancer cells." (PMID 18435854, 2008). "Our data suggest that TNK2 can enhance migration and invasion of breast cancer cells via preservation of EGFR expression, notwithstanding its previously reported signalling via BCAR1, explaining its oncogenic behaviour in vitro and correlation with metastatic human breast cancer in vivo." (PMID 18435854, 2008). "Based on our present findings we propose that TNK2 may employ at least two distinct mechanisms to enhance breast cancer cell migration and invasion, but we note that these are not necessarily mutually exclusive." (PMID 18435854, 2008). "The present study has demonstrated for the first time that breast cancer cell invasion can be enhanced by the ability of TNK2 to maintain EGFR cell surface expression and may provide the impetus for exploration of TNK2 as an alternative drug target for the treatment of EGFR-dependent cancers." (PMID 18435854, 2008). "In contrast, however, there is no affect of TNK2 siRNA on proliferation or apoptosis, which is in agreement with our findings that the main functional effect of EGFR activation in these breast cancer cells is stimulation of motility." (PMID 18435854, 2008). "In the present article we demonstrate the efficacy of targeting TNK2, a nonreceptor tyrosine kinase, by siRNA, and its effect on inhibiting EGFR cell surface expression and the migration and invasion of breast cancer cells." (PMID 18435854, 2008).
lung carcinoma (13 papers, 2014 to 2024). "Previous studies reported that the absence of TNK2 in lung cancer cells had an impact on MAPK signaling based on RNA-Seq analysis." (PMID 38650011, 2024). "All three variants were detected in primary tumors of two patients (UH1 & UH2), specifically in the DPYD (dihydropyrimidine dehydrogenase), MCL1 (v-myc myelocytomatosis viral oncogene homolog 1, lung carcinoma derived [avian]), and TNK2 (tyrosine kinase, non-receptor, 2) genes." (PMID 25950952, 2015).
non-small cell lung carcinoma (9 papers, 2014 to 2024). A group of at least three distinct histological types of lung cancer, including non-small cell squamous cell carcinoma, adenocarcinoma, and large cell carcinoma. "Moreover, TNK2 expression is independently associated with poor overall and relapse-free survival in non-small cell lung cancer." (PMID 34421982, 2021). "For example, TNK2 was the target of entrectinib, which has been approved to treat non-small cell lung cancer and solid tumors in the body." (PMID 39175079, 2024). "In non-small cell lung cancer, TNK2 might affects the development of tumors by influencing the tumor immune microenvironment." (PMID 34421982, 2021).
gastric cancer (8 papers, 2016 to 2023). A primary or metastatic malignant neoplasm involving the stomach. "In gastric cancer, the DNA copy numbers of TNK2 were significantly higher compared to those of normal gastric tissues." (PMID 36980241, 2023). "Similar findings are reported for gastric cancer (GC) where TNK2 was amplified in 36 (10.7%) of 335 primary GC tumours and is a marker for poor survival." (PMID 37194323, 2023).
ovarian carcinoma (7 papers, 2015 to 2025). A malignant neoplasm originating from the surface ovarian epithelium. "Oncogenic TNK2 mutations have also been reported in lung and ovarian cancers; these cancer-associated mutations could enhance TNK2 activity to promote proliferation and migration." (PMID 26356563, 2015).
colorectal cancer (5 papers, 2021 to 2023). A primary or metastatic malignant neoplasm that affects the colon or rectum. "When compared with different cancer cell lines, TNK2 was highly expressed in colorectal cancer cell lines from CCLE." (PMID 34421982, 2021). "Yu multi-cancer statistics showed that TNK2 expression in colorectal cancer is higher than that in breast, liver, esophageal, lung, and head and neck cancers." (PMID 34421982, 2021). "TCGA colorectal cancer statistics indicated that TNK2 expression in malignant colon tissues was higher than that in normal tissues." (PMID 34421982, 2021).
pancreatic cancer (5 papers, 2014 to 2023). "The gene encoding Ack1, TNK2, is amplified in human cancers, including prostate, breast, esophageal, lung, ovarian, and pancreatic cancers, with the highest gene amplification being 9% in ovarian and 14% in lung primary tumors." (PMID 36980241, 2023).
viral infection (5 papers, 2017 to 2025). "Here we demonstrated that TNK2, the human orthologue of sid-3, has an evolutionarily conserved function to facilitate virus infection in mammals." (PMID 31769754, 2019). "Consistent with the native TNK2 rescue, N-terminally GFP tagged TNK2 expression in the TNK2 KO1 cells statistically increased virus infection from 17.2% to 22.0% of GFP-transduced control cell infection (p<0.01)." (PMID 31769754, 2019). "Nevertheless, we consistently observed a small, but statistically significant increase in EMCV virus infection in TNK2 KO1 cells transduced with the canonical isoform one as compared to the control cells." (PMID 31769754, 2019). "The identification of sid-3 in this screen suggests a possible role for its human ortholog, TNK2, in virus infection." (PMID 28874467, 2017). "Since constitutively active point mutants of WASL have been described, we next tested whether overexpression of three such constructs in the TNK2 KO1 cells could further increase virus infection." (PMID 31769754, 2019). "Overexpression of wild type WASL in the TNK2 KO1 A549 cells led to increased EMCV virus infection." (PMID 31769754, 2019). "TNK2 mediates virus infection through endosomal trafficking pathways." (PMID 31769754, 2019). "We further demonstrated that TNK2, WASL, and NCK1 function in a pathway to support EMCV virus infection with WASL and NCK1 lying downstream of TNK2." (PMID 31769754, 2019). "The magnitude of the impact of TNK2 KO1 was greater than that of WASL KO or NCK1 KO, suggesting that TNK2 might work through additional pathways in mediating virus infection besides acting through WASL and NCK1." (PMID 31769754, 2019). "To determine whether TNK2, WASL, and NCK1 act in a common or distinct pathway for virus infection, we performed genetic epistasis analysis by generating double and triple mutant cell lines." (PMID 31769754, 2019). "In this study, we identified a TNK2 and actin-dependent pathway necessary to promote virus infection but does not appear to alter normal endocytosis." (PMID 31769754, 2019). "In this study, we further asked whether their respective human orthologues TNK2, WASL, and NCK1 play any roles in mammalian virus infection." (PMID 31769754, 2019). "TNK2, WASL, and NCK1 are in a pathway supporting virus infection." (PMID 31769754, 2019). "Since a role for TNK2 in clathrin-mediated endocytosis (CME) has been reported, we next examined whether the classic CME inhibitors such as dynasore (a canonical inhibitor of dynamin) or pitstop-2 (an inhibitor of clathrin) affect EMCV virus infection." (PMID 31769754, 2019). "To determine whether wsp-1, the C. elegans orthologs of genes that interact with TNK2 (lst-1, dhs-7, and nck-1), or C. elegans genes that interact with WSP-1 (mig-13, mig-2, and nck-1) affect Orsay virus infection, we performed RNAi knockdown and evaluated Orsay virus replication." (PMID 28874467, 2017).